ERG (ETS transcription factor ERG)
Diseases named in the same sentence as ERG in open-access papers (continued):
Sharing a sentence is not in itself a finding about the gene and the disease.
cancer (continued). "Inactivation of ERG may have a correlation with upregulation of Trop2 in certain cases and, thus, cancer progression." (PMID 26000093, 2015). "Subgroup analysis of ERG positive and ERG negative cancers revealed, that these associations were largely retained in the subsets of ERG negative and positive cancers." (PMID 25894226, 2015). "Elevated SENP1 expression levels were strongly linked to deletions of PTEN both in ERG positive and ERG negative cancers (p < 0.0001 each)." (PMID 26202067, 2015). "SOX9 expression levels were comparable in luminal cells of normal prostate glands (50% SOX9 positive) and 3,671 cancers lacking TMPRSS2:ERG fusion (55% SOX9 positive), but was markedly increased in 3,116 ERG-fusion positive cancers (81% SOX9 positive, p<0.0001)." (PMID 26030748, 2015). "Based on the morphological analysis, all ERG positive areas contained carcinoma tissue." (PMID 26294063, 2015). "Targeted inhibition of a DNA SSBR protein (XRCC1) by siRNA in ERG-overexpressing cancer cells may impair ERG induced SSBR and partially resensitize the cell radoresistance." (PMID 24739220, 2014). "Notably, the subset of patients with ERG rearrangement and high Ki-67 LI had the worst cancer-related survival." (PMID 24516518, 2014). "However, when stratifying for Ki-67 status, ERG rearrangement was a prognostic factor for cancer- related survival only in PCa patients with low Ki-67 LI." (PMID 24516518, 2014). "Of note, the association with low-grade cancers was limited to the subset of ERG fusion-negative tumors." (PMID 24179503, 2013). "The data revealed negative and weak p27 staining scores in 18.6 and 33.5% of samples, respectively, and showed that the loss of p27 expression was associated with ERG-negative cancers." (PMID 24179503, 2013). "Loss of p27 immunostaining was linked to tumors of low Gleason grade (P<0.0001) and ERG fusion-negative cancers (P<0.0001)." (PMID 24179503, 2013). "Others and us had described strong associations between deletions of PTEN and 3p13 and ERG positive cancers and between deletions of 5q21 and 6q15 and ERG negative tumors." (PMID 24261794, 2013). "The lower concordance of ERG positive carcinoma and PIN in tissue microarrays may be in part the consequence of multi-focal tumor heterogeneity." (PMID 22860005, 2012). "Three, cancer cells may result from luminal differentiation of a neoplastic progenitor-like cell type containing genetic alterations such as the TMPRSS2:ERG fusion." (PMID 21605402, 2011). "In addition, recent findings demonstrated a cooperation between TMPRSS2/ERG fusion and deregulated activity of cancer-related pathways, such as PTEN, PI3-Kinase, and AKT or AR." (PMID 21747944, 2011). "tERG, EWS/ERG and FUS/ERG fusions are all considered early events in cancer progression." (PMID 22140532, 2011). "Similarly, while EP cells failed to grow in vivo following orthotopic implantation and EP-AR cells formed discrete nodules, EP-AR TMPRSS2/ERG cells gave rise to large malignant tumors, stressing the synergistic nature of their cooperation." (PMID 21747944, 2011). "ERG, ETV1, ETV4, ETV6, FLI1, and FEV, are implicated in the pathogenesis of several cancers." (PMID 21789226, 2011). "Since its discovery, the TMPRSS2/ERG fusion has been extensively studied in several aspects, including early diagnosis, prognosis, contribution to cancer progression and even as a target for cancer therapy." (PMID 21747944, 2011). "Notably, EP-AR TMPRSS2/ERG cells formed large malignant tumors, which surrounded the normal murine prostate nodules (black arrowheads)." (PMID 21747944, 2011). "Furthermore, immunohistochemistry results showed CRISP3 protein overexpression in 63% of the carcinomas and chromatin immunoprecipitation with an anti-ERG antibody showed that CRISP3 is a direct target of the transcription factor ERG." (PMID 21814574, 2011).
cancer (continued). "We then distinguished a group of genes with a significant fold-increase in carcinomas and whose expression changes did not seem to be associated with ERG." (PMID 21814574, 2011). "Moreover, SPOCK1 expression was significantly elevated (p = 0.002) in ERG-high cancers and that of FBLN1 was significantly diminished (p = 0.047)." (PMID 20860828, 2010). "The largest subgroup of patients (54%), lacking both PTEN gene loss and ERG/ETV1 gene rearrangements comprised a ‘good prognosis’ population exhibiting favourable cancer-specific survival (85.5% alive at 11 years)." (PMID 20104229, 2010). "As expected, cancers with rearrangements of the ERG gene had fusions to 5′-TMPRSS2 sequences." (PMID 18594527, 2008). "However, in clinical outcome correlations only the presence of a duplication of rearranged ERG together with interstitial deletion of genomic sequences between the tandemly located TMPRSS2 and ERG sequences was correlated with worse cancer-specific death." (PMID 18594527, 2008). "Moreover, ERG can affect EMT, a process implicated in cancer metastasis." (PMID 38674385, 2024). "Most of these associations were also seen in the subsets of ERG-negative and ERG-positive cancers." (PMID 33339518, 2020). "Similarly, abundant studies demonstrated that E2F4, STAT1, MYC, ERG, and NFYB may play an important role in the pathogenesis and progression of various cancers, including OSCC, and the underlying mechanism may be related to dysregulated lncRNA." (PMID 32923393, 2020). "All these associations held true in the subset of ERG negative and ERG positive cancers." (PMID 30899444, 2019). "These associations were either weaker or absent in ERG-fusion positive cancers (data not shown)." (PMID 31640781, 2019). "Previous studies show that ERG regulates the expression of frizzled class receptor 4, E-cadherin, vimentin, ras homolog family member A, vascular endothelial growth factor receptor 2, and zinc finger E-box binding homeobox 1/2 during cancer metastasis and epithelial–mesenchymal transition process." (PMID 29773901, 2018). "Such an unequivocal independent association was lacking in ERG-positive cancer." (PMID 29304771, 2018). "Further analysis revealed that these associations were merely driven by the subset of ERG-negative cancers, High GGH expression was weakly linked to early biochemical recurrence in ERG negative cancers (p < 0.0001) and independent from established histo-pathological parameters." (PMID 28146062, 2017). "Subset analyses of ERG-negative and ERG-positive cancers showed, that all these associations were somewhat stronger in the subset of ERG negative cancers as compared to ERG-positive cancers." (PMID 28515422, 2017). "Novel genetic markers (such as Transmembrane protease serine 2 (TMPRSS2)-ERG fusion gene mRNA) or prostate cancer gene 3 (PCA3) had already entered the clinical practice, raising the question whether subsequent protein changes impact the evolution of the disease and the response to treatment." (PMID 28061466, 2017). "Besides, other studies have identified genes with significantly different methylation between different subtypes, and the differentially methylated genes (including CDKN2A, APC, CDH13, THBS2 and ERG) have been utilized to distinguish these different histological subtypes of cancers." (PMID 26862903, 2016). "They reported that TMPRSS2:ERG fusions occur in about 50 % of cancers and that they are unrelated to PSA recurrence in patients treated by radical prostatectomy while it is possible, that fusion positive cancers might react better to anti-androgen therapy than fusion negative tumors." (PMID 27530104, 2016). "Increasing amount of data is suggesting that these deletions may delineate biologically and clinically relevant subgroups within ERG positive and ERG negative cancers as most of these deletions are clearly linked to ERG status." (PMID 25825985, 2015).
cancer (continued). "Further subgroup analyses targeted highly recurrent chromosomal deletions that are tightly linked to the ERG status and that may delineate important molecular subgroups within ERG positive and ERG negative cancers." (PMID 26202067, 2015). "Post-translational modifications of ERG could lead to cancer progression." (PMID 26000093, 2015). "Furthermore, while ERG status may differ between distinct cancer foci in multifocal PC, we are confident of the match between 5hmC score and ERG status in the present study, as these were assessed on consecutive sections of the exact same cores." (PMID 26478752, 2015). "Therefore, the question still remains, if the TMPRSS2:ERG fusion alone is not sufficient to cause cancer, what changes does it induce in prostate epithelial cells to predispose them to become cancerous." (PMID 26310325, 2015). "Indeed, when stratified for subsets of ERG-fusion positive and negative cancers, most of the association disappeared." (PMID 26030748, 2015). "Loss of p27 staining was associated with ERG fusion-negative cancers." (PMID 24179503, 2013). "However, dual/complex TMPRSS2:ERG fusion, which has been shown to associate with poor survival, occurs with a substantially greater frequency in Met/CRPC patients (17%) than in primary cancer patients (3%)." (PMID 24098661, 2013). "It is possible that variable fractions of ERG fusion-negative or -positive cancers may obscure this association, particularly if only small sample sizes are analyzed." (PMID 24179503, 2013). "Furthermore, the gene co-expression signatures indicate that ERGIC1 and TMED3 are expressed together with genes involved in cellular redox homeostasis, in agreement to our earlier results demonstrating that ERG oncogene expressing cancer cells are sensitive to oxidative stress inducers." (PMID 22761906, 2012). "However, PLA2G7 positivity is not restricted to ERG positive cancer cells since other oncogenic mutations have been recently shown to induce PLA2G7 expression." (PMID 22202492, 2011). "The presence of PTEN gene loss in the absence of ERG/ETV1 gene rearrangements identified a patient population (6%) with poorer cancer-specific survival that was highly significant (HR=4.87, P<0.001 in multivariate analysis, 13.7% survival at 11 years) when compared with the ‘good prognosis’ group." (PMID 20104229, 2010). "Additionally, we have recently demonstrated that loss of 5′-ERG sequences coupled with duplication of TMPRSS2:ERG fusion sequences predicts extremely poor cancer-specific survival independently of Gleason score and PSA level at diagnosis in a conservatively managed watchful waiting patient cohort." (PMID 18594527, 2008). "One of the multiparametric tests, the MiPS (Michigan Prostate Score) includes analysis of PCA3, TMPRSS2/ERG and serum PSA to improve detection of high-grade cancers." (PMID 40115018, 2025). "Silphinene has demonstrated strong binding affinity to cancer-related proteins, including ERG, HER2, ABL1, and P13K-α, suggesting its potential as a molecular inhibitor in cancer therapy." (PMID 41455835, 2025). "Of the tumors with interpretable MTAP staining, 5,460 had data on ERG FISH and 10,418 cancers had ERG IHC data available." (PMID 40554389, 2025). "The most frequently detected gene fusions using the automated RNA workflow involved ERG, FGFR2, and ALK, consistent with the prevalence reported for similar pan-cancer cohorts." (PMID 39674366, 2025). "Reliable detection of ETS gene fusions by immunohistochemistry (IHC) is hindered by antibody availability; while a reliable antibody exists for detecting ERG, other ETS gene fusions lack specific antibodies for cancer cells." (PMID 40427154, 2025). "For example, ERG expression is seen in prostatic intraepithelial neoplasia (PIN) and proliferative inflammatory atrophy, lesions that can precede the development of cancer, and is uniform across all cells." (PMID 40858905, 2025).
cancer (continued). "In the primary cancer samples, the expression of PCA3, ERG, NPY, and AMACR was significantly upregulated, making them the characteristic genes with the largest expression differences." (PMID 39988626, 2025). "To verify the selected DEM (hsa-miR-21-5p), DEL (MIR99AHG) and 5 DEGs (RECK, TIMP3, EHD1, ERG and RASGRP1), we collected sequencing data from several cancer and normal tissues to explore the expression levels of these RNAs." (PMID 38495494, 2024). "Nanoparticles containing docetaxel conjugated to miRNA2c, which is a direct target of ERG and a critical inhibitor of EMT and prostate cancer cell motility, have increased bioavailability and inhibited not only cancer cells but also cancer stem cells." (PMID 38398019, 2024). "This molecular interplay between ERG and EZH2 underscores their importance in cancer progression and as targets for new therapies." (PMID 38216942, 2024). "Specifically, a DNA motif that specifically recognizes the ETS-related gene (ERG), a highly cancer-related transcription factor, was used as a ligand." (PMID 37495569, 2023). "In the setting of Pten deletion that by itself robustly mediates neoplasia in the mouse prostate, ERG and ETV1 overexpression reproducibly promotes cancer progression in numerous studies." (PMID 37018402, 2023). "Overexpressed ERG activates epithelial-to-mesenchymal transition (EMT) pathways, which leads to cancer progression and metastasis." (PMID 37509339, 2023). "Clusters 5, 6, and 11 expressed luminal epithelial markers, AR, AR-induced genes, and cancer cell markers (ERG and AMACR), supporting their identity as cancer cells." (PMID 36229464, 2022). "This latter suggests that ERG and PACE4 splicing are instead sharing common triggers, possibly related to the cancer cell DNA methylation status." (PMID 35410344, 2022). "O’PROTACs were tested on ERG and LEF1, two highly cancer-related transcription factors, and selectively promoted the degradation of these proteins, thereby inhibiting their transcriptional activity in cancer cells." (PMID 35188077, 2022). "The SERS signals for the RNA biomarkers T2:ERG and PCA3 in cancer patient urine samples were obtained by adsorbing T2:ERG and PCA3 amplicons onto 40 nm cationic silver nanoparticles." (PMID 34884946, 2021). "Previous studies showed that NSC139021 binds to RIOK2 and inhibits levels of ERG and RIOK2 protein in the context of ERG-positive cancer cells." (PMID 34572430, 2021). "Mohamed and colleagues screened small-molecule libraries for inhibition of ERG protein in TMPRSS2-ERG harboring VCaP cells and identified a small molecule that selectively inhibits erg-positive cancer cell growth." (PMID 33634124, 2021). "Perhaps, these findings indicate that the additive anti-cancer effect of JQ1 and Enza combination is primarily augmented in ERG-positive background." (PMID 34493733, 2021). "A highly selective small-molecule inhibitor of ERG, NSC139021, inhibits the growth of ERG-positive cancer cells." (PMID 33299103, 2020). "In human PCa tissues, we correlated CaSR expression with cancer cell proliferation and ERG expression that reflect the presence of the fusion gene TMPRSS2-ERG (observed in around half of PCa cases)." (PMID 32252342, 2020). "Data on both ERG FISH and IHC were available from 5416 cancers, and showed a concordant result in 5170 of 5416 (95.5%) cancers." (PMID 31893572, 2020). "Data on both ERG break-apart fluorescence in-situ hybridization (FISH) and ERG IHC were concordant in 95.5% of these 4,617 cancers with both FISH and IHC data." (PMID 32488048, 2020).
cancer (continued). "Data on ERG expression obtained by IHC and on transmembrane protease, serine 2:ETS‐related gene fusion (TMPRSS2:ERG) rearrangement obtained by FISH were available from 7935 and from 5360 cancers with interpretable CTCF staining results." (PMID 31736271, 2020). "A particularly prominent PNUTS staining was seen in cancers with PTEN (10q23) and 12p deletions, which was highly significant in all, ERG-negative, and ERG-positive cancers (p < 0.0001 each)." (PMID 32377272, 2020). "Data on both ERG FISH and IHC were concordant in 98.4% of these 4065 cancers with both FISH and IHC data." (PMID 32677026, 2020). "Data on both ERG FISH and IHC were available from 5191 cancers, and an identical result (ERG IHC positive and break by FISH or ERG IHC negative and missing break by FISH) was found in 4970 of 5191 (96%) cancers." (PMID 31736271, 2020). "The TMPRSS2:ERG status was available from 6196 cancers (using ERG break apart FISH analysis) and from 11,521 cancers (using ERG-IHC) of all tumors with interpretable data on hnRNPA1." (PMID 32417965, 2020). "Data on both ERG FISH and IHC were available in 4,998 cancers with concordant results in 95% of cases." (PMID 32377272, 2020). "ERG also modulates the expression of FOS and PCNA, which are focus molecules in Network IV that includes DNA replication, recombination, and repair, cancer, Organismal injury and abnormalities." (PMID 31303963, 2019). "ADTs are the standard of care in treating metastatic PCa but most cancer will progress to CRPC within a few years with restored AR activity and re-expression of AR-regulated genes, including ERG." (PMID 30718921, 2019). "A multi-center study of TMPRSS2:ERG (T2-ERG) and PCA3 in post-DRE urine from 1312 men showed significant improvement over serum PSA for the detection of clinically-relevant cancer at biopsy." (PMID 31013716, 2019). "GSE55945 contained ‘normal’ (non-cancer) prostate samples and low-grade primary PCa characterized by the absence or presence of the TMPRSS2:ERG fusion gene." (PMID 30733525, 2019). "Both, ERG FISH and IHC data were available from 5,365 of these cancers, and concordant results were found in 95.8% cancers." (PMID 31903168, 2019). "The downregulated genes were associated with cell cycle, TGF-β signaling, FoxO signaling, HIF-1 signaling, and cancer (CDKN1B, FLT3, PDK1, FOXO1, BCL2, ERG), suggesting potential positive regulation of these pathways by SHARP1 to maintain MLL-AF6 AML activity." (PMID 29692408, 2018). "Similar associations with ERG have also been found for other FAM members, including FAM77C and FAM13A that are up regulated in the presence of ERG, or for FAM111B, FAM3B and FAM124B that are down-regulated in ERG positive cancers." (PMID 28415558, 2017). "The algorithm based on the analysis of ERG, PCA3 and SPDEF showed its advantages in discriminating the high-grade cancer (≥GS7) from low-grade malignancy (GS6) and benign disease than tPSA in CaP screening." (PMID 28938580, 2017). "To better understand the impact of PTEN deletions on this association we compared the 8p deletion frequency in subsets of cancers defined by their PTEN deletion and ERG fusion status." (PMID 27880722, 2017). "From these samples, we identify established driver aberrations in a cancer-related gene in nearly all cases (97.7%), including driver gene fusions (TMPRSS2:ERG), driver focal deletions (PTEN, RYBP and SHQ1) and driver amplifications (AR and MYC)." (PMID 27328849, 2016). "In our study, the AAb panel comprising ERG, AMACR, and HERV-K Gag yielded an AUC of 0.792 for differentiating cancer cases from healthy controls." (PMID 28191285, 2016). "Deletions of 18q were found in 8.2% and 8.4% ERG-negative cancers (according to ERG IHC and FISH analysis), and in 6.4% (IHC) and 6.9% (FISH) ERG-positive cancers." (PMID 27861151, 2016). "Subset analyses revealed that the prognostic impact of SENP1 expression was solely driven by the subgroup of ERG positive, PTEN undeleted cancers." (PMID 26202067, 2015).